MIR3670-2 (microRNA 3670-2)
Synonyms: hsa-mir-3670-2
Gene: MicroRNA gene on chromosome 16 (16,306,370 to 16,306,434, forward strand). Ensembl gene ENSG00000264722.
Homologues: Paralogues in human: MIR3670-1 (100% identical), MIR3670-3 (100% identical), MIR3670-4 (100% identical).